RN7SL354P (RNA, 7SL, cytoplasmic 354, pseudogene)
Gene: Miscellaneous RNA gene on chromosome 15 (50,688,900 to 50,689,193, forward strand). Ensembl gene ENSG00000243027.
Homologues: Orthologues: chimpanzee Metazoa_SRP (99% identical), macaque Metazoa_SRP (95% identical), rabbit Metazoa_SRP (63% identical). Paralogues in human: RN7SL1 (81% identical), RN7SL2 (81% identical), RN7SL630P (81% identical), RN7SL3 (80% identical), Metazoa_SRP (78% identical), RN7SL333P (78% identical), RN7SL45P (78% identical), RN7SL679P (78% identical), RN7SL88P (78% identical), RN7SL14P (78% identical), RN7SL357P (78% identical), RN7SL408P (78% identical), and 704 more.